MET (MET proto-oncogene, receptor tyrosine kinase)
Diseases named in the same sentence as MET in open-access papers (continued):
Sharing a sentence is not in itself a finding about the gene and the disease.
cancer (continued). "This study focused on engineering an antagonistic anti-c-MET antibody capable of blocking HGF/c-MET signaling and inducing the killing of MET-overexpressing cancer cells through antibody-dependent cellular cytotoxicity (ADCC)." (PMID 39664377, 2024). "There are at least 11 bsAbs targeting CD19 × CD3, EGFR × MET, gp100 × CD3, CD20 × CD3, BCMA × CD3, CTLA-4 × PD-1, CD20 × CD3, and GPRC5D × CD3, which have been approved for treatment of various cancers." (PMID 38257366, 2024). "In cellular assays, crizotinib exhibited potent inhibitory activity against MET, ALK, and ROS1 kinases with IC50 values in the nanomolar range across various cancer cell lines." (PMID 39335535, 2024). "The MET-EGFR crosstalk is one of the most studied RTK interactions, particularly in cancer drug resistance." (PMID 39769452, 2024). "The relationship between c-MET and TGF-β in cancer cell immune evasion represents a compelling area of research with significant therapeutic implications." (PMID 39664377, 2024). "The activation of genes such as NR4A3, MET, ZEB1, CSF1, CSF2, CSF3, which can be involved in transcriptional dysregulation in cancer or hematopoietic cell lineage signaling pathways, can also be involved in cell differentiation." (PMID 37606991, 2023). "The overlapping genes included five known cancer driver genes (including HGF, MET, and PIK3R1) and five putative FOXP2 targets, such as MET and PIK3R1, identified by chromatin immunoprecipitation assays in both mice and humans." (PMID 37668356, 2023). "By inhibiting autophagy, MET protects cells from NMDAR2B cleavage, suggesting a potential mechanism by which MET contributes to cancer cell survival and adaptation to challenging conditions." (PMID 38201232, 2023). "The effect of DOXA on TNBC cell lines in vitro was evaluated in terms of cell viability, apoptosis, c-MET/EGFR signaling pathway, molecular docking studies and impact on cancer stem cell (CSC)-like properties." (PMID 37924112, 2023). "These 1,670 genes involved well-established cancer-related genes, including MYC, MYB, BRCA2, ERCC4, and MET for s1 subtype and TERT, BCL2, and SUZ12 for s3 subtype." (PMID 36731467, 2023). "Our previous findings indicate that SEMA3C functions as a secreted soluble autocrine growth factor that drives cancer growth by transactivating multiple RTKs such as EGFR, HER2 and MET via Plexin B1." (PMID 37443749, 2023). "Considering the oncogenic functions of MET and the emerging involvement of SMYD3 in GC, here we investigated the role of SMYD3 as a protein partner of MET in this cancer type and elucidated their structural and functional interplay." (PMID 37887325, 2023). "Expression levels of the EMT marker c-MET, cancer stemness markers ABCG2 and CD133a, which is both HH-GLI target and cancer stemness marker, were significantly decreased in the combined treatment of 5-FU and ATO." (PMID 36900263, 2023). "The seven subclusters included alveolar cells, pathological alveolar cells expressing both normal respiratory cell markers (SFTPB, AGR3) and genes related to cancer progression (SPINK1, MET), as well as five cancer subsets." (PMID 36973297, 2023). "Other high-penetrant cancer genes BRCA1, APC, STK11 and moderate-penetrant genes BRIP1, CDKN2A, FANCI and MET had a similar frequency 1 (5.8%)." (PMID 37277882, 2023). "Although novel c-MET (capmatinib, tepotinib) and EGFR inhibitors (osimertinib, lazertinib) have received limited approval for the treatment of various cancers, their high cost limits patient accessibility, particularly in the developing world." (PMID 37924112, 2023). "Accumulating evidence has revealed that the activation of the hepatocyte growth factor receptor, c-MET, plays a critical role in the acquisition of stem-like features of cancer cells." (PMID 38201226, 2023).
cancer (continued). "In the second sample, sent at timepoint 2 with disease progression, high level amplification of MET and BRAF was detected, suggesting potential selection of these alterations in the resistant cancer clone." (PMID 37147298, 2023). "HGF/c-MET interactions are activated by stromal cell HGF, which produces a suitable microenvironment for cancer cell growth and invasion, and in an autocrine manner by c-MET produced by cancer cells." (PMID 37828456, 2023). "Gene expression analysis showed that the levels of cancer stem cell and EMT markers ABCG2, CD133 and c-MET significantly increased after chemotherapy treatment and were impaired by HH-GLI inhibition and the combination of 5-FU and GANT61." (PMID 36900263, 2023). "With the advancement of cancer treatment exploration, the HGF/c-MET axis has emerged as a significant target." (PMID 37919751, 2023). "MET and NTRK fusions occurred at relatively low frequencies, but were detected in a number of cancer types surveyed." (PMID 36369474, 2022). "In short, in TNBC, CPT potently inhibited cancer stemness properties and cell invasion through the downregulation of the THEMIS2/MET signaling pathway." (PMID 34974522, 2022). "The existence of targetable oncogenic mutations was excluded by utilizing the Illumina amplicon cancer panel (TSACP), sequencing 212 regions in 48 cancer-related genes including EGFR, BRAF, KRAS, MET, and RET." (PMID 35039644, 2022). "This inhibited the cancer cell growth and metastasis along with the release of IFN-y and IL (interleukin)-2 from c-MET targeted CAR-T cells." (PMID 35081970, 2022). "Several studies suggest that MET, together with its ligand HGF, promotes cancer cell hallmarks including cell proliferation, survival, migration, angiogenesis in multiple mammalian cancer including hepatocellular carcinoma, head and neck cancer etc.." (PMID 35432450, 2022). "We show that Met signaling converges on HER3–tyrosine phosphorylation across a panel of seven MET-amplified cancer cell lines and that HER3 is required for cancer cell expansion and oncogenic capacity in vitro and in vivo." (PMID 35249128, 2022). "Oncogenes, such as MET, PLK1 and CCNE1, demonstrated higher expression levels in cancer tissues than in normal tissues in the TMA and TCGA data sets." (PMID 36137139, 2022). "Notably, a comprehensive meta-analysis involving 6010 BC patients revealed that c-MET overexpression was associated with 1.41-fold increased risk of recurrence in ER+/HER2- resected BC patients, likely due to the induction of EMT gene expression signature supporting cancer metastases." (PMID 36498560, 2022). "Therefore, the c-MET/HGF axis could be a potential target for cancer therapy." (PMID 36233320, 2022). "Previous publications already report the transcriptional regulation of cancer- and metastasis-related genes by MACC1 in CRC, like the hepatocyte growth factor receptor c-MET, the adhesion factor SPON2 and the stem-cell transcription factor NANOG." (PMID 35597866, 2022). "As already reported for other types of cancer cells, ARQ treatment showed a specific effect on MET in our cell lines since it lowered MET phosphorylation, suggesting down-regulation of MET activity." (PMID 35574376, 2022). "MET is a receptor tyrosine kinase also known as the hepatocyte growth factor (HGF) receptor and is directly involved in the invasive growth of cancer cells." (PMID 35495117, 2022). "c-Met, alternatively known as MET or hepatocyte growth factor receptor (HGFR), is a membrane-bound tyrosine kinase known to have critical roles in organogenesis and cancer development." (PMID 36483567, 2022). "Several TKIs or anti-cancer drugs, including cabozantinib and gefitinib, can inhibit HGF/c-MET-, ANG-2/Tie-2-, and/or EGF/EGFR-mediated signaling." (PMID 35008398, 2022). "Overexpression of FER has been identified in several cancer types, and FER has been shown to activate MAP kinase signaling by phosphorylating receptor tyrosine kinases including EGFR and MET." (PMID 35706047, 2022).
cancer (continued). "Fusion pairs were also identified in colon (CAPZA2-MET and MET-MET), lung (PIK3CA-TBL1XR1 and RET-NCOA4) and pancreatic (FNDC3B-PIK3CA and TBL1XR1-PIK3CA) cancers." (PMID 35984852, 2022). "In short, we discovered that THEMIS2 controls cancer stemness and chemoresistance mainly by regulating PTP1B–p-MET interaction and MET activation." (PMID 34974522, 2022). "Since MET is a known master regulator gene for the invasive growth of cancer cells, the role of NMDAR in MET-induced migration and invasion was evaluated in TNBC cells." (PMID 36139568, 2022). "We have identified that multiple RTKs, such as EGFR, FGFR2, EPHA2, and MET, are key targets for C1GALT1 and their appropriate O-glycosylation is essential for cancer progression and metastasis." (PMID 35169131, 2022). "Cabozantinib is used for cancer treatment and inhibits various receptor tyrosine kinases, including VEGFR, MET, RET, KIT, AXL and FLT332." (PMID 35449173, 2022). "Like MET, RON orchestrates cell signaling pathways that promote oncogenesis and enable cancer cell survival; however, it has a more unique role in the regulation of inflammation." (PMID 35454943, 2022). "The interactive crosstalk between MET and EGFR family members is well documented and has been raised as a mechanism of resistance to targeted monotherapies in other cancers." (PMID 35954439, 2022). "Increased activities of c-MET (mesenchymal–epithelial transition protein) and its ligand hepatocyte growth factor (HGF) promote cancer cells’ proliferation and metastasis in numerous cancers." (PMID 36233320, 2022). "It has been reported that in cancers ‘addicted’ to MET signaling, RON phosphorylation is dependent on the level of expression and activation of MET." (PMID 35454943, 2022). "In this study, we comprehensively investigated the incidence of MET alterations (gene amplification, SNV, and fusion) in a consecutive series of 2,239 patients with cancer who were candidates for palliative chemotherapy." (PMID 36483096, 2022). "While we have observed a role for MPZL3 in a HER3-dependent proliferative response in MET-amplified cells, it is unclear whether this is a specific requirement of Met-dependent transformation independent of HER3 or whether MPZL3 expression is associated with RTK amplification in cancer." (PMID 35249128, 2022). "This study aimed to investigate the incidence of MET aberrations, including copy number variations (CNVs), especially gene amplification, and/or fusions using a 500-gene NGS panel as real-world, pan-cancer data." (PMID 36483096, 2022). "For RTKs, EGFR, MET and EPHA2 were phosphorylated in almost all cell lines, highlighting a pattern of multiple cancer pathway activation." (PMID 33750427, 2021). "This once again suggests a cooperation between c-MET and ILEI in the regulation of E-cadherin transcription, however, these data also point out that cancer cells show very different sensitivity towards this regulation." (PMID 33596971, 2021). "These two protease inhibitors have been reported to be aberrantly expressed in many types of cancer and represent one of the mechanisms of HGF/MET signaling." (PMID 34381422, 2021). "These agents have been developed against a variety of target-kinases other than (or in addition to) RET, such as VEGF receptors, AXL, FGFR1, EGFR, MET, c-KIT and BRAF, and unfortunately demonstrated limited potency for RET-positive cancers." (PMID 33806299, 2021). "The aberrant activation of the c-MET pathway and crosstalk with other RTKs has been shown to stimulate the PI3K/AKT and RAS/MAPK signaling pathways, which contribute to cancer biology." (PMID 34439385, 2021). "The expressions of ALDH1, c-MET and CD44 were enhanced in cancer cell clusters attached to the metastases compared with those in sherbet-like aggregates in Amatuximab mice." (PMID 33637083, 2021).
cancer (continued). "The synergistic effect between dP@mVLP/RNAic-MET and TMZ was identified at multiple doses with complete cancer eradication with 5 mg/kg of dP@mVLP/RNAic-MET at a normal TMZ patient dose." (PMID 34055785, 2021). "Next, we investigated invasiveness and its sensitivity to c-MET and ILEI signaling inhibition in the five selected cancer cell lines." (PMID 33596971, 2021). "qRT‐PCR showed that circFAT1 KD significantly inhibited the expression of the cancer stemness‐related genes, including SOX2, KLF4, MET, BMI1, CD24, OCT4, and ALDH1, in ALDHhigh SCC23 cells." (PMID 34258151, 2021). "KRIBB11 effectively decreased the HSP70/BAG3/BCL2 and EGFR/MET/AXL proteins, leading to apoptosis of resistant cancer cells." (PMID 34203709, 2021). "Copy number amplification events in CCND1, CCND3, CDK6, ERBB2, FGFR1, MET, and PIK3CA also showed higher expression compared to wild types across various cancer types." (PMID 34429404, 2021). "Abnormal expressions of c-MET and EGFR were reported in various human cancers where they support the proliferation and survival of cancer cells." (PMID 34512327, 2021). "S100A2, TGFA, MET, PCNA, SCD, GDF15, and PAI1 act as oncogenes by promoting cancer metastasis or proliferation 24-30." (PMID 34131400, 2021). "A prospective phase II trial, European Organization for Research Treatment of Cancer (EORTC) 90101 “CREATE”, evaluated the oral MET/ALK/ROS1 inhibitor crizotinib in patients with CCSA." (PMID 34885165, 2021). "The CTD2 data set had a total of 79 unique drugs with sensitivities across 351 cancer cell lines that involve 22 targets, such as EGFR, HDAC1, MTOR, MET, ERBB2, and BRAF." (PMID 33795761, 2021). "The hybrid molecules correctly bind MET and HGF, inhibit HGF-induced MET downstream signaling, and quench HGF-driven biological responses, such as growth, motility and invasion, in cancer cells of different origin." (PMID 33446252, 2021). "Exploiting a co-culture system of human pancreatic stellate cells and cancer cells, we demonstrated that fibroblast activation was reduced upon HGF/MET axis inhibition." (PMID 34298732, 2021). "Mechanistically, we find that bromodomain-containing protein 4 (BRD4) recruits Mediators and NF-κB p65 to form SEs at cancer stemness genes such as TP63, MET and FOSL1, in addition to oncogenic transcripts." (PMID 34172737, 2021). "For example, in models transplanted with different cancer cell lines or spontaneous cancer models, changes in neutrophil recruitment induced by specifically knocking out neutrophil MET, the HGF receptor, increase cancer growth." (PMID 34674757, 2021). "In this study we sought to determine the anti-cancer effects of DPT on HCC827GR cells, which are resistant to gefitinib (EGFR-TKI) due to regulation of EGFR and MET and their related signaling pathways." (PMID 33746190, 2021). "In response to intra-tumoural hypoxia, cancer cells express hypoxia-inducible factor-1α (HIF-1α), which induces the expression of the pro-angiogenic vascular endothelial growth factor (VEGF), MET and HGF." (PMID 33526881, 2021). "All cell lines showed distinct interaction patterns with prey receptors, and MET, CD44, and integrin5a showed the highest average shifts in cancer cell lines—13.38%, 11.10%, and 10.15%, respectively." (PMID 33603128, 2021). "Crizotinib is a dual inhibitor of MET and anaplastic lymphoma kinase (ALK) that has shown promise in multiple cancer types, including breast cancer." (PMID 34508101, 2021). "For example nocodazol, a colchicine binding site agent was found to simultaneously inhibit various cancer-related kinases, including ABL1, c-KIT, BRAF, MEK1 (MAP2K1), MEK2 (MAP2K2), and MET." (PMID 33671106, 2021).
cancer (continued). "To study the adaptive changes during targeted inhibition of oncogenic signaling we exposed cancer cells (n = 9) driven by diverse activated kinases (EGFR, MET, BRAF, HER2, ALK) to targeted drugs and performed transcriptional profiling using RNA-seq." (PMID 34535668, 2021). "In this setting the combination of sotorasib and MET inhibitors such as crizotinib and capmatinib has shown to overcome resistance to KRASG12C inhibitors in vitro in cancer cells with MET amplification." (PMID 35004309, 2021). "Further in vitro mechanistic investigations and xenograft experiments with combined counteraction of ILEI and c-MET activities suggest that c-MET and ILEI cooperate to increase the invasiveness of cancer cells." (PMID 33596971, 2021). "Genes such as EGFR, PIK3CA, DROSHA, MDM4, and APC were located inside recurrently aberrant regions, while other known cancer-genes such as NF1, MET and mTOR were identified as cis-genes and located outside the most recurrently altered regions." (PMID 34625038, 2021). "In conclusion, these results demonstrate the apoptotic effects of DPT on HCC827GR cells and signify the potential of DPT to serve as an adjuvant anti-cancer drug by simultaneously inhibiting EGFR and MET." (PMID 33746190, 2021). "In a cancer context, HGF/c-MET activation exerts pro-angiogenic effects, leading to a direct activation of ECs and an indirect stimulation of other pro-angiogenic factors, as VEGF." (PMID 33916438, 2021). "The positive rate for MET and FASN in cancer tissues of TNBC were higher significantly than those in the adjacent tissue." (PMID 34123778, 2021). "The binding of HGF to its receptor leads to dimerisation and phosphorylation of c-MET and subsequent activation of several signalling pathways including MAPK and PI3K that regulate proliferation, invasion, and migration of cancer cells." (PMID 33271944, 2020). "Here, we used single-molecule super-resolution microscopy to simultaneously visualize single MET and epidermal growth factor receptor (EGFR) clusters in two cancer cell lines, HeLa and BT-20, in fixed and living cells." (PMID 32316583, 2020). "MAPK signaling pathway, pathway in cancer, and toll like receptor signaling pathway, and so on, were enriched in HGF and c-MET high expression phenotype." (PMID 32788873, 2020). "This binding resulted in the expression of several target genes involved in angiogenesis, proliferation, migration and invasion of cancer cells, such as VEGFA, EGFR, c-Myc, Cyclin D1 and MET." (PMID 33088626, 2020). "We studied the interactions of MET and EGFR upon stimulation by HGF or EGF in the two cancer cell lines, HeLa and BT-20, which exhibit inverse MET:EGFR expression ratios." (PMID 32316583, 2020). "Tyrosine-protein kinase or hepatocyte growth factor receptor (Known as HGFR or MET), a proto-oncogene expressed in both stem and cancer cells, is a crucial regulator of invasive growth." (PMID 32328196, 2020). "The c-MET (mesenchymal epithelial transition) protein is another key factor in the progression of NSCLC, making this a promising target for new cancer therapies." (PMID 33153004, 2020). "The effect of sERr on major proto-oncogenes, such as c-MET and EGFR, invokes a mechanism for cancer treatment." (PMID 32161259, 2020). "Crizotinib is an ATP-competitive inhibitor targeting ALK/ROS1/c-MET kinases that has been approved by the FDA as a first-line chemical for the treatment of NSCLC and other cancers with ALK rearrangement, ROS1 rearrangement, or aberrant activation of c-MET2-5." (PMID 32792859, 2020). "In this study, we propose a novel strategy through the use of a nucleolin-targeting aptamer (AS1411, N) and c-MET-targeting aptamer (c-MET apt, C) in a synergistic manner as an effective combinatorial treatment for cancer." (PMID 32708267, 2020). "We confirmed that iBET-151 reduced the expression of RTK mRNA and proteins, including EGFR, ERBB3, MET, and IGF-1R, thereby regulating cancer cell growth and survival." (PMID 33412753, 2020).